HDAC4 (histone deacetylase 4)
Diseases named in the same sentence as HDAC4 in open-access papers (continued):
Sharing a sentence is not in itself a finding about the gene and the disease.
breast carcinoma (40 papers, 2013 to 2026). "As expected, loss of HDAC4 facilitated breast cancer cell invasion in vitro." (PMID 36604412, 2023). "Furthermore, HDAC4 is overexpressed in esophageal carcinomas and breast cancers and is associated with a poor prognosis." (PMID 31703394, 2019). "Elevated HDAC4 activated the NF-κB signaling pathway, resulting in increased PD-L1 transcription and enhanced immune evasion of breast cancer cells." (PMID 41501889, 2026). "Other miRNAs include miR-9-5p (HDACs in gastric cancer), miR-101 (EZH2 in glioblastoma), miR-22 (TIP60 and HDAC4 in breast cancer), and miR-125 (HDAC4 and HDAC5 in breast cancer)." (PMID 40761244, 2025). "The relation between miR-22 and HDAC4 was confirmed also in breast cancer, downregulation of miR-22 increases HDAC4 levels." (PMID 36762207, 2023). "All these results suggest that pan-HDAC inhibitors with HDAC4 inhibitory activity are capable of producing deleterious effects on breast cancer progression." (PMID 36604412, 2023). "Taken together, the findings support the theory that increased NEDD9 expression induced by HDAC4 inhibition promotes breast cancer cell mobility." (PMID 36604412, 2023). "In both SOS and CAF, μsPEF exposure-induced nuclear accumulation of HDAC4 is enhanced by H-89 treatment in the breast cancer cell line." (PMID 36466344, 2022). "HDAC4 inhibition decreased cell proliferation, migration and metastasis in breast cancer, colorectal cancer as well as myeloma 30-32." (PMID 35864951, 2022). "Further, the miR-125a-5p levels in breast cancer can be a useful prognostic biomarker and offer a novel therapeutic avenue by targeting the HDAC4 in breast cancer." (PMID 35913967, 2022). "Using whole transcriptome data from a murine mammary carcinoma cell line (pG-2), we identified upregulation of Hdac4, 7 and 8 in tumor cells surviving conventional chemotherapy." (PMID 35016723, 2022). "These outcomes suggest that dysregulations of HDAC2, HDAC4, and HDAC5 can collaborate with the development of tamoxifen resistance in ER+ breast cancer cells associated with miR-10b and miR-125a-5p deregulation." (PMID 34359587, 2021). "The recent study revealed that HDAC2 and HDAC4 promote the oncogenicity of breast cancer cells by upregulating EphA2 expression and phosphorylation." (PMID 32376822, 2020). "miRNA-22, miRNA-10b and miRNA-125a-5p was suggested to interact with HDAC4 and contributed an impact on the drug-resistance in breast cancer cells." (PMID 33193750, 2020). "The recent study revealed that upregulation of EphA2 by HDAC2 and HDAC4 plays a crucial role in breast cancer, and HDACs-EphA2 signaling axis is a promising therapeutic target for advanced breast cancer." (PMID 32376822, 2020). "High incidence of class IIa HDACs (HDAC4, HDAC5 and HDAC9), is associated with colorectal and breast cancers." (PMID 30691229, 2019). "The evidence presented in the current study indicated a negative regulation of HDAC4 and FOXP1 by miR-22 in fulvestrant-resistant breast cancer cells, which supports previous reports showing that HDAC4 and FOXP1 were direct targets of miR-2249,50." (PMID 30057418, 2018). "For example, homozygous deletion of HDAC4 is a frequent event in malignant melanoma, whereas inhibition of HDAC4 expression by miR-125a-5p was anti-neoplastic in breast cancer cells and HDAC4 promotes proliferation of gastric cancer cell lines." (PMID 30064501, 2018). "For instance HDAC4 whose expression seems to be higher in basal breast cells has also been shown to stimulate MCF7 breast cancer cell proliferation." (PMID 26930713, 2016). "We found a few studies/data sets supporting down-regulation of HDAC4 in breast cancer samples, relative to normal controls (p ≤ 0.05)." (PMID 26206152, 2015). "HDAC4 also induced resistance to 5-fluorouracil in breast cancer cells and inhibited docetaxel-related cytotoxicity in gastric cancer cells." (PMID 26206152, 2015).
breast carcinoma (continued). "Towards this end, further characterization of the function of HDAC4 in drug resistance will be an important step forward towards realizing the goal of personalized medicine in the management of breast cancer patients, particularly those with recurrent disease." (PMID 26206152, 2015). "Breast cancer patients with low expression of HDAC4 had poor relapse free survival, compared to those with high expression (p < 0.01)." (PMID 26206152, 2015). "In the current study we show that miR-125a-5p is negatively correlated with breast cancer progression and functions to inhibit tumor growth as well as metastasis by targeting HDAC4." (PMID 25504437, 2015). "This study leads to the discovery of a novel molecular mechanism in which the miRNA miR-125a-5p suppresses HDAC4 expression which can be exploited as a therapeutic approach of human breast cancer." (PMID 25504437, 2015). "We also evaluated the correlation of HDAC4 expression with relapse free survival of breast cancer patients." (PMID 26206152, 2015). "Collectively, the data mining from public databases supports our conclusions, suggesting that lower HDAC4 levels correlate with advanced breast cancers with poor prognosis." (PMID 26206152, 2015). "We first searched for evidence of under-expression of HDAC4 in breast cancer patients, relative to normal patients, using the online data mining platform Oncomine." (PMID 26206152, 2015). "We further demonstrate the tumor suppression activity by miR-125a-5p expression or down-regulation of HDAC4 in human breast cancer." (PMID 25504437, 2015). "Looking within tumor types, high HDAC4 activation was seen in basal breast cancer and mesenchymal glioblastoma (GBM), while high EZH2 activation was seen in luminal breast cancer and proneural GBM." (PMID 24079712, 2013). "In particular, EZH2 activation is seen in luminal breast cancers and proneural GBM, while HDAC4 activation is seen in basal breast cancers and mesenchymal GBM." (PMID 24079712, 2013). "We demonstrate that some tumor types, such as neuroblastoma, have consistently high EZH2 activation, while pharyngeal cancer and subsets of glioblastoma, non-small cell lung cancer (NSCLC), and breast cancer have high HDAC4 activation." (PMID 24079712, 2013). "The role of HDAC4 (Histone Deacetylase 4) in breast cancer remains unclear, as its function is context dependent, whether promoting or suppressing tumour growth." (PMID 40790295, 2025). "Furthermore, it initiates cell proliferation in breast cancer through mTORC1-S6 kinase 1, Erk1/c-Myc axis, Hsp27, and HDAC4/5/7, and it positively regulates the immune suppressor PDL1 in oral squamous cell carcinoma (OSCC)." (PMID 36672148, 2023). "The link between miR-22 and HDAC4 has also been confirmed in breast cancer." (PMID 36762207, 2023). "However, μsPEF exposure to 10 pulses induces nuclear accumulation of HDAC4 in which CaMKII affects nuclear accumulation while high [Ca2+]i likely inhibits AMPK-based export of HDAC4 to the cytoplasm of the breast cancer cells." (PMID 36466344, 2022). "Among them, HDAC4-mediated deacetylation of the SMAD4 promoter may lead to 5-FU resistance in breast cancer cells." (PMID 26044366, 2015). "Together these results demonstrate that serum miR-125a-5p level in breast cancer may be a useful prognostic biomarker and offer a novel therapeutic avenue by targeting HDAC4 in breast cancer." (PMID 25504437, 2015). "We propose miR-10b-HDAC4 nexus as one of the molecular mechanism of tamoxifen resistance which can potentially be expolited as a novel targeted therapeutic approach for the clinical management of tamoxifen-resistant breast cancers." (PMID 26206152, 2015). "In conclusion, our investigation has identified that miR-125a-5p in serum may be a convenient and reliable biomarker for prognosis in breast cancer and that miR-125a-5p plays an important role to suppress tumorigenesis by directly targeting HDAC4." (PMID 25504437, 2015).
breast carcinoma (continued). "HDAC4 plays an important role in breast cancer growth and invasion." (PMID 25504437, 2015). "Importantly, depleting HDAC4 attenuated these tumor-enhancing activities, indicating that HDAC4 is a functional target of miR-125a-5p to suppress growth and tumor progression of breast cancer." (PMID 25504437, 2015). "Interestingly, miR-125a-5p not only targets HDAC4 down-regulation but also decreased the expression of HDAC5 in human breast cancer." (PMID 25504437, 2015). "Using breast cancer and glioblastoma as examples to examine intrinsic subtypes of particular cancers, EZH2 activation was highest in luminal breast cancers and proneural glioblastomas, while HDAC4 activation was highest in basal breast cancer and mesenchymal glioblastoma." (PMID 24079712, 2013). "Levels of HDAC4 and HDAC5 have been reported as transcriptionally overexpressed in human breast cancer compared to normal or benign breast tissue." (PMID 36466344, 2022). "And silencing either HDAC4 or HDAC5 was able to promote the nuclear import of SerRS as well, strongly indicating that HDAC4 and HDAC5 regulate the acetylation of SerRS at lysine 323 and hence its nuclear localization in breast cancer cells." (PMID 34400610, 2021). "Given that the expression level of SerRS also showed slight decrease in breast cancer, the application of HDAC4/5 inhibitors combined with small molecules that increase SerRS expression, such as all-trans retinoic acid and emodin, could achieve promising effects in the therapy of breast cancers." (PMID 34400610, 2021). "Similar to HDAC4, HDAC5 also displays a regulatory effect on tumor resistance in breast cancer, which is related to its regulation of cell proliferation, cell differentiation and autophagy." (PMID 33193750, 2020). "We therefore sought to investigate whether the inhibition of HDAC2, HDAC4, or KDM1A would restore the expression of PHLDA1 in lapatinib-resistant HER2+ breast cancer cells." (PMID 37047202, 2023). "Importantly, HDAC4-related inhibitors can inhibit the activation of downstream IL-6/STAT3 signaling to suppress the growth and metastasis of breast cancer." (PMID 37843550, 2023). "In conclusion, we demonstrated that inhibition of HDAC4 stimulated NEDD9-FAK signaling pathway, leading to metastasis of breast cancer cell, and consequently limiting the clinical efficacy of pan-HDAC inhibitors against breast cancer." (PMID 36604412, 2023). "Thus, AMPK-mediated (and perhaps PKA-mediated) nuclear export of HDAC4, which is mitigated following μsPEF exposure, appears to dominate intracellular HDAC4 localization within MCF7 breast cancer cells." (PMID 36466344, 2022). "In this context, in vivo studies in mice models of breast cancer have demonstrated that lentiviral delivery of the tumor suppressor miR-125a-5p reduced tumor growth, metastasis, and angiogenesis by directly targeting HDAC4 (Histone deacetylase 4)." (PMID 34072348, 2021). "Histone decetylase 4 (HDAC4) could mediate the deacetylation of SMAD family 4 so that induce the 5-fluorouracil resistance in both ER+ and ER- breast cancer cells." (PMID 28423597, 2017). "While there is evidence connecting miR-10b with clinical outcome in breast cancer patients, no such information is available for HDAC4." (PMID 26206152, 2015). "Moreover, the gene methylation of KIF2C was significantly elevated in luminal A breast cancer samples with prognostic value, together with three other cell cycle and proliferation regulators Ki-67, UBE2C (ubiquitin conjugating enzyme E2C) and HDAC4 (histone deacetylase 4)." (PMID 38344808, 2024). "Decrease of PARP enzyme activity and phosphorylation of class-IIa HDAC4/5/7 were necessary and sufficient for the synergy observed between SIK2 inhibitors and PARP inhibitors for downregulating cancer cell growth in ovarian and breast cancer cell lines and xenografts." (PMID 35642638, 2022).
breast carcinoma (continued). "Moreover, HDAC4 degradation by certain chemotherapeutic agents results in the apoptosis of head-and-neck cancer cells that are resistant to TRAIL, while miR-22-driven HDAC4 repression helped to resensitize fulvestrant-resistant breast cancer cells." (PMID 32641122, 2020). "In another study on breast cancer, it was found that PTP4A3 can induce the transformation of normal cancer cells into stem-like cells by competitively binding to MEF2A with HDAC4 (histone deacetylase 4), a process independent of PTP4A3’s phosphatase activity." (PMID 38611852, 2024).
gastric cancer (28 papers, 2014 to 2025). A primary or metastatic malignant neoplasm involving the stomach. "It is also noteworthy that HDAC4 is upregulated in gastric cancer and is associated with a poor prognosis." (PMID 39497715, 2024). "The clinical relevance of this regulatory loop is highlighted by the fact that mutation or deletion of HDAC4 favors the survival of patients with gastric cancer." (PMID 31703394, 2019). "Importantly, mutations or deletions of HDAC4 in gastric cancers correlate with a better patient survival, and that is even more discriminant than any particular molecular subgroup (e.g., MSI)." (PMID 31703394, 2019). "Interestingly, in addition to the elevated expression of HDAC4, we observed that 7.7% of gastric cancers available in the TCGA data were shown to have point mutations, frame shift deletion or deep deletion in the HDAC4 gene that might affect its function." (PMID 31703394, 2019). "Functional measurements showed that Class IIA (HDAC4) is upregulated in gastric cancer cells and related to poor prognosis." (PMID 38193944, 2024). "HDAC4 has been considered as a promising therapeutic target for multiple cancers, including gastric cancer, nasopharyngeal carcinoma and colon cancer, due to its effects on promoting the growth and metastasis of tumors." (PMID 37843550, 2023). "Other studies in gastric cancer have shown that HDAC4 inhibition can also increase cisplatin and docetaxel cytotoxicity." (PMID 36982651, 2023). "lncRNA MIAT, a sponge for miR‐29a‐3p, regulated the biological behaviors of gastric cancer cell by up‐regulating HDAC4 expression." (PMID 31984680, 2022). "Amongst the mechanisms impacting the response to therapy, increased expression of several histone deacetylases (HDACs) has been described in gastric cancers, such as HDAC4." (PMID 34575561, 2021). "Knockdown of MIAT suppresses cell biological behaviours in gastric cancer via a mechanism involving the miR-29a-3p/HDAC4 axis." (PMID 33154765, 2020). "Firstly, HDAC4 expression is elevated in gastric cancer biopsies compared to normal tissues, showing differences between molecular subgroups." (PMID 31703394, 2019). "We then analyzed HDAC4 expression data of the TCGA (The Cancer Genome Atlas) database for gastric cancers and found that HDAC4 expression varied depending on the molecular subgroup of gastric cancer." (PMID 31703394, 2019). "HDAC4 has been considered as a critical regulator of cell proliferation in various cell types, such as satellite cells, gastric cancer cells, and neural progenitors." (PMID 30156956, 2019). "First, we analyzed the TCGA data for gastric cancers by sorting for genes whose expressions are correlated positively or negatively with HDAC4 expression." (PMID 31703394, 2019). "For example, it was reported that MIAT regulates cell proliferation, migration, and invasion in gastric cancer through a mechanism involving the miR-29a-3p/HDAC4 axis." (PMID 31886187, 2019). "To further characterize the role of HDAC4 in gastric cancer, we analyzed HDAC4 mRNA levels by RT-qPCR in both tumor and adjacent healthy tissue biopsies from a cohort of 31 gastric cancer patients." (PMID 31703394, 2019). "This approach gave us an overview on the top ranked pathways potentially affected by the expression level of HDAC4 in patients with gastric cancer." (PMID 31703394, 2019). "The cisplatin-induced regulation of HDAC4 expression in gastric cancer cells involves complex and balanced mechanisms." (PMID 31703394, 2019). "To validate the impact of cisplatin on HDAC4 expression in gastric cancer cells, we treated the cells with cisplatin at two doses (IC50 and IC75) for 24 h." (PMID 31703394, 2019). "We gathered molecular and clinical evidence indicating that histone deacetylase 4 (HDAC4) is a good candidate to explain some of the features leading to a differential sensibility of gastric cancers towards cisplatin." (PMID 31703394, 2019).